DHRS4-AS1 (DHRS4 antisense RNA 1)
Synonyms: C14orf167; PRO1488; AS1DHRS4; C14orf67; DHRS4AS1
Gene: Long non-coding RNA gene on chromosome 14 (23,938,219 to 24,075,861, reverse strand). Ensembl gene ENSG00000215256.
Diseases named in the same sentence as DHRS4-AS1 in open-access papers:
DHRS4-AS1 is named in the same sentence as 3 diseases in open-access papers, as found by Europe PMC text mining. Sharing a sentence is not in itself a finding about the gene and the disease. The quoted sentences say what the papers report.
endometriosis (1 paper, 2022). The growth of functional endometrial tissue in anatomic sites outside the uterine body. "This study aimed to explore the mechanisms of DHRS4 antisense RNA 1 (DHRS4-AS1) in endometriosis." (PMID 35414313, 2022). "However, to the best of our knowledge, the role of the lncRNA DHRS4 antisense RNA 1 (DHRS4-AS1) in EC-ESCs and endometriosis remains unknown." (PMID 35414313, 2022).
DHRS4-AS1 also shares sentences with these, for which no sentence is quoted: cancer (1 paper); clear cell renal carcinoma (1).